ATAT1 (alpha tubulin acetyltransferase 1)
Description:
Specifically acetylates 'Lys-40' in alpha-tubulin on the lumenal side of microtubules. Promotes microtubule destabilization and accelerates microtubule dynamics; this activity may be independent of acetylation activity. Acetylates alpha-tubulin with a slow enzymatic rate, due to a catalytic site that is not optimized for acetyl transfer. Enters the microtubule through each end and diffuses quickly throughout the lumen of microtubules. Acetylates only long/old microtubules because of its slow acetylation rate since it does not have time to act on dynamically unstable microtubules before the enzyme is released. Required for normal sperm flagellar function. Promotes directional cell locomotion and chemotaxis, through AP2A2-dependent acetylation of alpha-tubulin at clathrin-coated pits that are concentrated at the leading edge of migrating cells. May facilitate primary cilium assembly.
Synonyms: Alpha-TAT; Alpha-TAT1; C6orf134; MEC17; Nbla00487; FLJ13158; Em:AB023049.7
Tractability: Small molecule: a structure with a bound ligand is known. PROTAC: ubiquitination databases record sites on it; its protein half-life has been measured.
Safety:
Unwanted effects reported when the protein is acted on. In parentheses: how it was acted on, where the effect was seen, and who reports it.
thrombocytopenia (source: ClinPGx)
Gene: Protein-coding gene on chromosome 6 (30,626,842 to 30,646,835, forward strand). Ensembl gene ENSG00000137343.
Subcellular location: Cytoplasm; Membrane, clathrin-coated pit; Cell junction, focal adhesion; Cell projection, axon; Cytoplasm, cytoskeleton; Cytoplasm, cytoskeleton, spindle
Subcellular location (Human Protein Atlas): Cytosol; Golgi apparatus
Pathways (Reactome):
Organelle biogenesis and maintenance: Cargo trafficking to the periciliary membrane
Gene Ontology:
Molecular function: L-lysine N-acetyltransferase activity, acting on acetyl phosphate as donor; protein binding; tubulin N-acetyltransferase activity; acetyltransferase activity
Biological process: alpha-tubulin acetylation; cilium assembly; microtubule cytoskeleton organization; neuron development; regulation of microtubule cytoskeleton organization; response to mechanical stimulus; response to pain
Cellular component: cytosol; mitotic spindle; axon; clathrin-coated pit; cytoplasm; cytoskeleton; focal adhesion; membrane; microtubule; microtubule bundle; spindle
Genetic constraint (gnomAD): Loss-of-function variants: 43 observed, 56.89 expected, observed/expected ratio (o/e) 0.76, 90% interval 0.59 to 0.98. The upper end of that interval is the gene's LOEUF score, 0.98, which puts it in group 4 of 6, group 1 being the genes least tolerant of losing a copy. Missense variants: 446 observed, 504.81 expected, observed/expected ratio (o/e) 0.88, 90% interval 0.82 to 0.95. Synonymous variants: 168 observed, 179.46 expected, observed/expected ratio (o/e) 0.94, 90% interval 0.82 to 1.06.
Homologues: Orthologues: chimpanzee ATAT1 (99% identical), pig ATAT1 (93% identical), dog ATAT1 (90% identical), rat Atat1 (90% identical), mouse Atat1 (90% identical), rabbit ATAT1 (82% identical), guinea pig ATAT1 (81% identical), tropical clawed frog atat1 (43% identical), zebrafish atat1 (32% identical), Drosophila melanogaster Atat (23% identical), Drosophila melanogaster lky (23% identical), Caenorhabditis elegans mec-17 (19% identical), and 1 more.